PCNA (proliferating cell nuclear antigen)
Diseases named in the same sentence as PCNA in open-access papers (continued):
Sharing a sentence is not in itself a finding about the gene and the disease.
tumor (continued). "Therefore, we performed immunohistochemistry on the tumor tissues to measure the proliferation expression of PCNA and TUNEL assay to measure apoptosis." (PMID 30018975, 2018). "PCNA immunofluorescence was used to quantify cell proliferation in tumor sections from all groups." (PMID 30483133, 2018). "Furthermore, our in vivo results showed that LAC117 induced apoptosis in tumor xenograft models and significantly increased expression of cleaved caspase-3 together with decreased proliferation (PCNA) in tumor tissues." (PMID 29739391, 2018). "Moreover, a gene expression profile performed on galectin-3 transfectants revealed activation of genes involved in tumor growth and progression, among which were PCNA (proliferating cell nuclear antigen), replication factor C and Rb retinoblastoma gene." (PMID 29393868, 2018). "In general, the expression level of PCNA in tumor is correlated with the degree of malignancy." (PMID 29546069, 2018). "In addition, the proliferative activities of the tumor cells were assessed using immunohistochemistry for proliferating cell nuclear antigen (PCNA) and Ki-67 in formalin-fixed, paraffin-embedded xenograft tumor tissues." (PMID 29415994, 2018). "We observed tumor cells strongly positive for proliferating cell nuclear antigen (PCNA) at the TB-interface in the control group, and hOCIF treatment significantly reduced the number of PCNA positive cells at the TB-interface." (PMID 29547583, 2018). "Tumor cells upregulate PCNA levels and PCNA is used as a prognosis marker in various cancers." (PMID 29875773, 2018). "Moreover, this combination therapy resulted in an obviously loose cell arrangement with the lowest percentage of PCNA-positive tumour cells, presumably due to the effective reduction of both ECM and tumour cells." (PMID 30139933, 2018). "Tumor proliferation marker PCNA and migration marker (MMP2 and MMP9) were detected." (PMID 30572883, 2018). "In vitro, by silencing of CD164, the proliferation, migration, and invasion of tumor cells were inhibited significantly by regulating related proteins such as Ki67, proliferating cell nuclear antigen, matrix metalloproteinases‐2, and matrix metalloproteinases‐9." (PMID 30022623, 2018). "Indeed, p140Cap expression delays spontaneous tumour appearance and show decreased tumour masses, consistent with a decreased staining of the proliferative marker PCNA, with respect to NeuT mice." (PMID 28300085, 2017). "Hematoxylin and eosin staining was performed to confirm xenograft tumor morphology, and immunohistochemical staining was performed to show the decreased positive rates of proliferation markers ki-67 and proliferating cell nuclear antigen (PCNA)." (PMID 28388536, 2017). "Furthermore, proliferation of tumor cells evaluated by PCNA expression and MI were significantly diminished in tumors of histamine, clozapine and JNJ28610244 treated mice." (PMID 28460440, 2017). "Moreover, in vivo nuclear IP3 buffering also suppressed tumor cell proliferation as shown by the reduced number of PCNA positive cells per μm2 subjected to IP3-sponge-NLS treatment (control = 2796 ± 338 cells; IP3-sponge-NLS = 1583 ± 112 cells)." (PMID 28376104, 2017). "Additionally, inhibition of PCNA expression and apoptotic cell death of tumor cells in the tumor xenograft tissues were observed in the chaetocin-treated mice." (PMID 28419143, 2017). "PCNA immunostaining was used to examine cell proliferation in tumor tissues." (PMID 28915590, 2017). "There was an increase in γ-H2AX phosphorylation, an indicator of DNA breaks, as well as a reduction in positive staining for PCNA, a marker for cellular proliferation, in both the lemongrass and the white tea extract-treated groups compared to the control group in the tumor sections." (PMID 29340014, 2017). "PCNA has high expression in almost all tumor tissues because of its function." (PMID 29019895, 2017).
tumor (continued). "Moreover, the higher PCNA LI was positively correlated with the higher tumor grade (r = 0.8247; p < 0.001)." (PMID 28651614, 2017). "On the other hand, in the protein expression profile of SSC-2, the neoplastic proliferation of tumor cells was related to the overexpression of PCNA, MPM2, KRAS, STAT3, EGFR, and bFGF and was supported by the overexpression of the protein translation factors eIF5A, DHS, and DOHH compared to SSC-1." (PMID 28789700, 2017). "IHC staining with specific antibody against PCNA indicated in the eIF3d depletion tumor sections that there were fewer proliferative cells, however, increased staining intensity for cleaved caspase-3 was observed, indicating significantly increased apoptosis cells in eIF3d shRNA xenograft tumors." (PMID 28594409, 2017). "HT-29 tumor cells treated with OXA again demonstrated increased PCNA expression." (PMID 29403306, 2017). "Moreover, IHC staining of the tumor tissues illustrated that percentage of PCNA positively stained cells in FN (+) sh-Control group was significantly higher than both FN (-) sh-Control group and FN (+) sh-CIP2A group." (PMID 28521777, 2017). "The marginal region of tumor tissue manifested marked immunoreactivity for pAKT, pGSK-3β, and PCNA." (PMID 29053747, 2017). "Additionally, the proliferative activities of tumor cells were assessed via immunohistochemical staining for Ki-67 and PCNA in FFPE tissues of xengraft tumors." (PMID 29371929, 2017). "We further examined the effects of astaxanthin on cell proliferation and apoptosis in tumor tissues derived from control and astaxanthin-treated mice using anti-PCNA (proliferating cell nuclear antigen), anti-Ki67, cleaved caspase-3 antibody, and the TUNEL assay, respectively." (PMID 28282880, 2017). "Moreover, we demonstrated by both western blot and immunohistochemical analysis that expression level of PCNA in the tumours of rOly-treated mice is significantly lower than in tumours originating from mice belonging to the control group." (PMID 28416764, 2017). "Moreover, it was noteworthy that B55δ inhibited tumor growth while reducing the expression of the proliferation-related protein PCNA." (PMID 27074866, 2016). "Finally, the proliferative activity of the tumor cells was assessed via immunohistochemical staining of Ki-67 and PCNA." (PMID 27857177, 2016). "Also, HS-173 significantly increased expression of TUNEL, cleaved caspase-3 along with decreased expression of PCNA in tumor tissues." (PMID 27793006, 2016). "Serial tumor sections were also probed for proliferating cell nuclear antigen (PCNA) expression." (PMID 27473057, 2016). "Decidua and tumor tissues are both characterized by high levels of PCNA expression." (PMID 27765926, 2016). "Two cellular proliferation antigens, Ki67 and PCNA, were detected by IHC in the tumor tissues from xenografts; the expression of both of these antigens was significantly stronger in xenografts of pcshRNA-NC-transfected cells than in xenografts of pcshRNA eIF5B-transfected cells." (PMID 27694689, 2016). "Further, in rats with DMBA-induced mammary gland tumors, pretreatment with hesperetin (50 mg/kg BW/day) significantly reduced the tumor burden and the overexpression of the proliferating cell nuclear antigen (PCNA), as well as restoring the decreased Bcl-2 and increased Bax expression." (PMID 27827912, 2016). "As a result, tumors from CPS-treated mice exhibited notably lower expression of PCNA and Ki67 by immunohistochemical staining compared with tumors from control mice, which confirmed a significant decrease in proliferation of tumor xenografts by CPS." (PMID 27729033, 2016). "In vivo assays showed that FA-CD-PLLD/DOC/MMP-9 could inhibit HNE-1 tumor growth and decrease PCNA expression effectively." (PMID 27259274, 2016). "In addition, the sensitizing effect of GCS inhibition by PDMP was accompanied by reduced tumor cell proliferation, as denoted by PCNA detection and vascularization, as detected in CD34 stained slides." (PMID 26811497, 2016).
tumor (continued). "As a tumor achieves a proliferative state by acquiring self-sufficiency in cell growth and/or by becoming resistant to cell death, we analyzed the expression of PCNA (proliferation index) and TUNEL (death index)." (PMID 26992208, 2016). "Additionally, the proliferative activities of the tumor cells were assessed via immunohistochemical staining for Ki-67 and PCNA." (PMID 27057632, 2016). "In addition, hBD3 is expressed in proliferating cell nuclear antigen (PCNA)-positive basal cells in normal oral mucosa and in tumor cells of oral carcinoma in situ lesions." (PMID 27034006, 2016). "We and others published that PCNA can be used by tumor cells to suppress NK cell functions." (PMID 27765926, 2016). "To confirm the mechanism by which SL4 retards tumor growth, we also examined the expression levels of proteins in the xenograft tumors, including the cell cycle proteins p21 and cdc25C, and the cell proliferation marker PCNA." (PMID 27819344, 2016). "Although this technique was specifically customized for this work, the framework itself is generalizable and can have several other applications such as estimation of the tumor area and the number of PCNA positive nuclei, etc., in xenograft model, which indicates its broad functionality." (PMID 27661103, 2016). "These tumours also exhibited a reduction in Ki67 and PCNA expression by immunohistochemistry." (PMID 27095304, 2016). "To further confirm whether HS-543 inhibits tumor growth through the induction of apoptosis and inhibition of proliferation, we identified the expression of cleaved caspase-3 and PCNA in the isolated tumor tissues." (PMID 25483100, 2015). "Decrease in insulin levels, may be partly responsible for the anti-tumor effect, thereby reducing the rate of tumor growth as observed from the reduced BrdU and PCNA staining in the tumors of 2-DG fed mice, indeed supporting this proposition." (PMID 26135741, 2015). "The decrease in tumor size was associated with a reduction in cell proliferation as evidenced by lack of PCNA expression and increased cell death reflected by positive TUNEL staining." (PMID 25926554, 2015). "The decreased PCNA indicated the tumor DNA synthesis was inhibited byμsPEF." (PMID 25928327, 2015). "An in vivo study showed that FALHE suppressed the expression of the tumor markers PCNA and Ki67." (PMID 25996383, 2015). "Overexpressed PCNA is detectable from the tumor tissue, which may serve as a marker of CCA in clonorchiasis." (PMID 26313366, 2015). "The drastic decrease in the expression of the cell proliferation biomarker, PCNA [Proliferating cell nuclear antigen] observed in the tumour tissues of mice treated with DW-F5 [Group 5A] as assessed by IHC analysis also correlated with the extent of tumour reduction." (PMID 26061820, 2015). "Hematoxylin and eosin (H&E) staining and immunostaining with anti-proliferating cell nuclear antigen (PCNA) antibody revealed the presence of large lipid droplets, high nuclear density and strong PCNA staining in the tumor sections from the mouse group fed the HFD." (PMID 26472027, 2015). "Elevated numbers of hepatic neutrophils wereevident throughout the disease process and underwent a steady increase until 40weeks where they were accompanied by enlarged livers, substantial tumourfrequency, large tumours and high numbers ofPCNA+ proliferating hepatocytes (PCNA+)." (PMID 25879839, 2015). "The expression level of PCNA in tumor tissue were also decreased." (PMID 26368019, 2015). "Here, we monitored a significant PCNA drop after DVDMS plus multiple ultrasound treatments compared with either mono-treatment, indicating that disaggregation of PCNA may contribute to tumor cell apoptosis." (PMID 26631871, 2015). "Notably, in three weeks after implantation, the mice injected with 5-8F-BART7-3p cells appeared to carry larger tumor burdens and display relatively higher expression levels of Ki67 and PCNA in tumor tissues relative to the controls." (PMID 25691053, 2015).
tumor (continued). "Results from immunohistochemical analysis of tumor sections demonstrated a decreased intensity-staining pattern of cell proliferation markers such as PCNA, Ki67 and cyclin D1 in fisetin and sorafenib treated tumors as compared to their respective untreated control groups." (PMID 26299806, 2015). "Furthermore, cellular proliferation was evaluated by measuring the expression levels of PCNA and Ki-67; decreased protein expression levels of PCNA and Ki-67 were most significant in the radiation plus 3-MA-treated tumor samples." (PMID 25891159, 2015). "Increased cell proliferation, as revealed by PCNA staining, was evident in all the tumor types." (PMID 26097888, 2015). "In order to evaluate the effect of FA + ASP chemopreventive regimens on tumor cell proliferation, immunohistochemistry (IHC) was performed to measure the expression of cell proliferation markers proliferating cell nuclear antigen (PCNA) and MKI67 on pancreatic tissues." (PMID 26301084, 2015). "In addition, tumor tissues treated with miR-34a showed a significantly decreased immunostaining of Ki67 and PCNA, suggesting the in vivo anti-proliferation effect of miR-34a." (PMID 25686834, 2015). "In addition, immunohistochemistry showed that the tumor growth marker, proliferating cell nuclear antigen, was significantly reduced in the knockdown model." (PMID 25794010, 2015). "Since the high proliferation is a hallmarker of cancer cells and DACH1 was reported to inhibit tumor growth in vivo in a series of xenograft models, we examined PCNA expression, a surrogate marker of cellular proliferation, in a series of sections from the same sample." (PMID 25322986, 2014). "The proliferation rates of tumor cell were assessed in situ by PCNA antigen labeling index." (PMID 24892421, 2014). "As uncontrolled tumor cell proliferation is a characteristic feature of most cancers, we also analyzed the A375 tumor xenografts for the potential antiproliferative effects of GSPs using western blot analysis of PCNA and immunohistochemical detection of PCNA-positive cells." (PMID 25361006, 2014). "Given the association between high nestin expression and elevated staining for the proliferative cell markers, Ki-67 and PCNA, we focused on the role of nestin in tumor cell proliferation using retroviruses to introduce shRNA vectors with nestin-targeting (or control) sequences into NSCLC cells." (PMID 24498263, 2014). "We found that CCL18 could promote tumor growth in vivo by enhancing angiogenesis and expression of cell proliferation markers PCNA and Ki67." (PMID 25197632, 2014). "We previously reported a novel cancer associated PCNA isoform (dubbed caPCNA), which was significantly expressed in a broad range of cancer cells and tumor tissues, but not in non-malignant cells." (PMID 24728180, 2014). "Given the essential role of PCNA in coordinating these cellular processes that are fundamental to the proliferation and survival of cancer cells, inhibition of PCNA is viewed as an effective way to suppress tumor growth." (PMID 24728180, 2014). "PCNA, a trimer that forms a clamp around DNA and promotes DNA polymerase-dependent DNA replication, is highly expressed in proliferating cells, especially tumor cells; in the latter, high expression of PCNA is correlated with high malignancy." (PMID 24966803, 2014). "Moreover, analysis of in situ cell proliferation using anti-PCNA antibody demonstrated the inhibition of malignant cell proliferation in the MDA-MB-231-ShB tumor compared to the MDA-MB-231-ShNC tumors." (PMID 24628760, 2014). "We previously reported a novel cancer associated PCNA isoform (caPCNA), which is present in a broad range of cancer cells and tumor tissues, but not highly expressed in non-malignant cells." (PMID 24728180, 2014). "Tumor cell labeling indexes (LIs) of Ki-67 and PCNA were also obtained." (PMID 24741354, 2014). "In consistence with previous reports, PCNA was positively related to the tumor grade." (PMID 25322986, 2014).
tumor (continued). "Moreover, we found that the proliferation of KGN cells, a human ovarian granulosa-like tumour cell line, was suppressed after overexpression of miR-181a, with a concomitant reduction of PCNA protein level." (PMID 23527246, 2013). "Either HPV or PCNA has been investigated as a LSCC tumor marker in many studies." (PMID 24353714, 2013). "Moreover, daily treatment of metformin led to a substantial inhibition of tumor growth in a xenograft model with concomitant decrease in the expression of proliferating cell nuclear antigen (PCNA), cyclin D1 and p-mTOR." (PMID 24351837, 2013). "Notably, the morphological analysis demonstrated that TIM-3 was also present on CD68+ macrophages, CD31+ endothelial cells, CK-18+ epithelial cells, as well as on Bcl-2+ and PCNA+ tumor cells." (PMID 24137353, 2013). "The level of PCNA is one of the methods to define the tumor proliferation." (PMID 24353714, 2013). "We already have reported that CUR induces apoptosis, causes downregulation of EGFR, Akt, cMET cyclin D1, and PCNA protein expression in CL-5 xenograft tumors, and inhibits lung cell invasion and metastasis through upregulation of HLJ1 expression in tumor cells." (PMID 23970932, 2013). "Double staining revealed that EpCAM and PCNA were co-expressed in numerous tumor cells, suggesting that EpCAM-positive tumor cells may have the potential to proliferate." (PMID 23251255, 2013). "Immunostaining was used to analyze PCNA protein expression in resected tumor tissues." (PMID 24098911, 2013). "Results of histochemical analysis of tumor sections demonstrated that there was a significant decrease in the numbers and intensity of cell proliferation markers such as Ki67 and PCNA in delphinidin treated tumors as compared to their respective untreated control groups." (PMID 24124611, 2013). "All of the proteins, hMSH2, hMLH1, PCNA and Ki67, were expressed in the nuclei of tumor cells." (PMID 24205245, 2013). "These mouse tumours are highly proliferative as evidenced by PCNA staining." (PMID 24163262, 2013). "However, there are contradictory reports questioning the fidelity of PCNA as a clinical marker in tumor progression." (PMID 23593472, 2013). "Immunohistochemistry tests were used for PCNA, Ki67, Caspase 3 expression in tumor tissue." (PMID 24351817, 2013). "Finally, proteasome and proliferating cell nuclear antigen (PCNA) protein levels increased in p-WT Xn compared to parental tumour tissue." (PMID 23239665, 2013). "Additionally, the level of PCNA reflects the proliferative activity of the tumor cells, and is considered to be a reliable indicator of cell proliferation." (PMID 24137341, 2013). "The expression of PCNA in tumour tissues was improved, and fucoidan could inhibit the expression of PCNA." (PMID 23737842, 2013). "Double staining showed that EpCAM and PCNA were co-expressed in numerous tumor cells." (PMID 23251255, 2013). "The decrease in the expression of HSP27 and positive PCNA may work together to control tumor proliferation and the malignant transformation process." (PMID 23599795, 2013). "To examine the mechanism by which α-tomatine suppressed the growth of PC-3 cell tumors in mice, we next examined tumor tissue recovered from mice carrying subcutaneous tumors for expression of markers of proliferation (PCNA and Ki-67) and apoptosis (cleaved-PARP and cleaved-caspase-3)." (PMID 23437404, 2013). "Lesser number of PCNA immunoreactivity was observed in metformin-treated mice, which accounted for 19% decrease (p < 0.05) in PCNA-positive cells compared with control, demonstrating significant inhibitory effects of metformin on tumor cell proliferation in vivo." (PMID 24351837, 2013).